ENSA (endosulfine alpha)
Description:
Protein phosphatase inhibitor that specifically inhibits protein phosphatase 2A (PP2A) during mitosis. When phosphorylated at Ser-67 during mitosis, specifically interacts with PPP2R2D (PR55-delta) and inhibits its activity, leading to inactivation of PP2A, an essential condition to keep cyclin-B1-CDK1 activity high during M phase (By similarity). Also acts as a stimulator of insulin secretion by interacting with sulfonylurea receptor (ABCC8), thereby preventing sulfonylurea from binding to its receptor and reducing K(ATP) channel currents.
Synonyms: MGC4319; MGC8394; MGC78563; ARPP-19e
Tractability: PROTAC: ubiquitination databases record sites on it.
Gene: Protein-coding gene on chromosome 1 (150,600,851 to 150,629,612, reverse strand). Ensembl gene ENSG00000143420.
Subcellular location: Cytoplasm
Subcellular location (Human Protein Atlas): Nucleoli; Nucleoplasm; Cytosol; Microtubules
Pathways (Reactome):
Cell Cycle: MASTL Facilitates Mitotic Progression
Gene Ontology:
Molecular function: potassium channel inhibitor activity; protein binding; signaling receptor binding; ion channel inhibitor activity; phosphatase inhibitor activity; protein phosphatase 2A binding; protein phosphatase inhibitor activity; protein phosphatase regulator activity
Biological process: regulation of insulin secretion; G2/M transition of mitotic cell cycle; mitotic cell cycle; response to nutrient
Cellular component: cytoplasm; nucleoplasm
Genetic constraint (gnomAD): Loss-of-function variants: 7 observed, 16.64 expected, observed/expected ratio (o/e) 0.42, 90% interval 0.24 to 0.79. The upper end of that interval is the gene's LOEUF score, 0.79, which puts it in group 3 of 6, group 1 being the genes least tolerant of losing a copy. Missense variants: 87 observed, 141.46 expected, observed/expected ratio (o/e) 0.62, 90% interval 0.52 to 0.74. Synonymous variants: 58 observed, 55.04 expected, observed/expected ratio (o/e) 1.05, 90% interval 0.85 to 1.31.
Homologues: Orthologues: dog ENSA (100% identical), mouse Ensa (98% identical), guinea pig ENSA (98% identical), chimpanzee ENSA (97% identical), pig ENSA (95% identical), rat Ensa (95% identical), macaque ENSA (85% identical), tropical clawed frog ensa (85% identical), zebrafish ensab (74% identical), zebrafish ensaa (67% identical), Caenorhabditis elegans ensa-1 (36% identical). Paralogues in human: ARPP19 (70% identical).
Diseases named in the same sentence as ENSA in open-access papers:
ENSA is named in the same sentence as 3 diseases in open-access papers, as found by Europe PMC text mining. Sharing a sentence is not in itself a finding about the gene and the disease. The quoted sentences say what the papers report.
type 2 diabetes (1 paper, 2024). "ENSA (Endosulfine Alpha) is also a protein-coding gene that plays a very important role in modulating insulin secretion through the interaction with KATP (ATP-sensitive potassium channel) channel, and this gene has been proposed as a candidate gene for type 2 diabetes." (PMID 38956704, 2024).
ENSA also shares sentences with these, for which no sentence is quoted: breast carcinoma (1 paper); Obesity (1).